MIR128-2 (microRNA 128-2)
Synonyms: hsa-mir-128b; hsa-mir-128-2; MIR128B; MIRN128-2; MIRN128B; mir-128-2; mir-128b
Gene: MicroRNA gene on chromosome 3 (35,744,476 to 35,744,559, forward strand). Ensembl gene ENSG00000207625.
Gene Ontology:
Cellular component: RISC complex
Homologues: Orthologues: chimpanzee ptr-mir-128-2 (100% identical), dog MIR128-2 (100% identical), macaque mml-mir-128b (100% identical), rabbit MIR128-2 (100% identical), pig ssc-mir-128-2 (96% identical), guinea pig MIR128-2 (90% identical), tropical clawed frog xtr-mir-128-2 (85% identical), zebrafish mir128-2 (70% identical). Paralogues in human: MIR128-1 (69% identical).